CSNK1A1 (casein kinase 1 alpha 1)
Diseases named in the same sentence as CSNK1A1 in open-access papers (continued):
Sharing a sentence is not in itself a finding about the gene and the disease.
atherosclerosis (2 papers, 2024 to 2025). A disease characterized by the build-up of fatty material and calcium deposition in the arterial wall resulting in partial or complete occlusion of the arterial lumen. "To explore the potential mechanism by which CSNK1A1 contributes to atherosclerosis, we first transfected VSMCs with siRNA to knock down CSNK1A1." (PMID 41213929, 2025). "Further studies are warranted to clarify the in vivo function of CSNK1A1 in the progression of atherosclerosis." (PMID 41213929, 2025). "Three pivotal atherosclerosis-associated genes—CD36, S100A10, CSNK1A1—were unveiled, offering valuable clinical insights." (PMID 39660117, 2024). "However, it remains unclear whether CSNK1A1 modulates atherosclerosis progression by regulating autophagy." (PMID 41213929, 2025). "Moreover, ssGSEA analysis of model genes in the marker gene set of the GSEA database revealed that CD36 and S100A10's activities in the respective marker gene sets were precisely opposite to CSNK1A1, highlighting distinct regulatory roles of these genes in the context of atherosclerosis." (PMID 39660117, 2024). "The entire process harnessed multiple machine learning algorithms to elucidate the fundamental signature genes intrinsic to atherosclerosis, ultimately pinpointing CD36, S100A10, and CSNK1A1 as genetically correlated markers." (PMID 39660117, 2024). "In summary, our study highlights monocyte infiltration as a crucial contributor to atherosclerosis development, with CD36, S100A10, and CSNK1A1 emerging as prominent biomarkers for disease detection." (PMID 39660117, 2024). "Second, although we demonstrated that knockdown of CARMN resulted in significant downregulation of CSNK1A1 in vivo, we did not directly validate the biological role of CSNK1A1 in atherosclerosis." (PMID 41213929, 2025). "To confirm whether CARMN plays a role in atherosclerosis by regulating CSNK1A1 expression, we stimulated VSMCs with ox-LDL and detected the expression of CARMN and CSNK1A1 using qRT-PCR." (PMID 41213929, 2025). "In summary, as shown in the schematic diagram, our study demonstrated that CARMN knockdown suppressed CSNK1A1 expression, thereby promoting VSMC-derived foam cell formation and atherosclerosis via the transcriptional downregulation of autophagy mediated by the AKT/ATG7 pathway." (PMID 41213929, 2025).
autoimmune disease (2 papers, 2024 to 2025). A disorder resulting from loss of function or tissue destruction of an organ or multiple organs, arising from humoral or cellular immune responses of the individual to their own tissue constituents. "A recent study revealed that CSNK1A1 inhibits autoimmune diseases by promoting the autophagic degradation of STING1." (PMID 41213929, 2025).
cervical cancer (2 papers, 2019 to 2020). A primary or metastatic malignant neoplasm involving the cervix. "However, in this study, the expression of CSNK1A1 in cervical cancer tissue was significantly higher than it was in CIN tissue, but the expression of CTNNB1 in CIN and SCC tissues was not significantly different." (PMID 32993576, 2020).
myeloid neoplasm (2 papers, 2017 to 2022). Proliferation of myeloid cells originating from a primitive stem cell. "In summary, comprehensive molecular analyses using SNP-A karyotyping, WES and targeted sequencing revealed recurrent somatic mutations involving CSNK1A1 and G3BP1 in the CDR and DDX41 in the CRR in myeloid neoplasms with the del(5q)." (PMID 28031539, 2017).
Obesity (2 papers, 2023 to 2024). Accumulation of substantial excess body fat. "More importantly, FOXO1, CSNK1A1, NF1L3 and NR1D1 clock genes/proteins are not involved in this type of obesity." (PMID 39062927, 2024).
acute lymphoblastic leukemia (1 paper, 2018). Leukemia with an acute onset, characterized by the presence of lymphoblasts in the bone marrow and the peripheral blood. "Del(5q) can be detected in not only MDS but also acute lymphoblastic leukemia, especially at 5q32 where the CSNK1A1 gene exists." (PMID 29793495, 2018).
bladder cancer (1 paper, 2014). "Specific point mutation frequencies are even lower and do not exceed 2.4% (as for CSNK1A1 in bladder cancer, for CSNK1D in lung squamous carcinoma and colorectal or pancreatic cancer; point mutations in CSNK1E seem to be very rare)." (PMID 25306547, 2014).
cervical diseases (1 paper, 2020). "However, there is no research on the expression of CSNK1A1 and cervical diseases." (PMID 32993576, 2020).
cicatricial alopecia (1 paper, 2025). Scarring hair loss, also known as cicatricial alopecia, is the loss of hair which is accompanied with scarring. "In addition, our findings confirm the crucial role of CSNK1A1 and SFN in normal hair follicle development and their association with cicatricial alopecia." (PMID 41380997, 2025). "Downregulation of SFN and CSNK1A1 may serve as potential biomarkers for studying cicatricial alopecia and provide clues for understanding its molecular mechanisms." (PMID 41380997, 2025). "Our results showed that CSNK1A1 and SFN exhibit abnormal expression in the hair follicles of patients with cicatricial alopecia, indicating the possibly important role of CSNK1A1 and SFN in the normal developmental process of hair follicles." (PMID 41380997, 2025). "We also found that CSNK1A1 and SFN exhibit abnormal expression in the hair follicles of patients with cicatricial alopecia, which further proves the role of CSNK1A1 and SFN in the normal development of hair follicles." (PMID 41380997, 2025). "However, our results showed that the expression levels of CSNK1A1 and SFN were downregulated in cicatricial alopecia compared with the normal controls." (PMID 41380997, 2025). "Notably, this study indicates that CSNK1A1 and SFN exhibit abnormal expression in the hair follicles of patients with cicatricial alopecia, which further validates the role of CSNK1A1 and SFN in the normal developmental process of hair follicles." (PMID 41380997, 2025).
Coronary Artery Disease (1 paper, 2025). "For Coronary Artery Disease (CAD), five genes intersected between RFE and DEA analyses: CSNK1A1, AKAP5, TOPORS, ACTBL2, and FNTA." (PMID 40287491, 2025).
epilepsy (1 paper, 2025). A brain disorder characterized by episodes of abnormally increased neuronal discharge resulting in transient episodes of sensory or motor neurological dysfunction, or psychic dysfunction. "Here we report two de novo mutations in the casein kinase 1 isoform alpha (CSNK1A1) gene which underlie severe epilepsy with similar clinical presentation in two patients." (PMID 40156289, 2025).
hemangioblastoma (1 paper, 2019). "Surface B is also phosphorylated by AURKA and CSNK1A1 at Ser72, and patients with mutations affecting this residue develop hemangioblastomas and RCC." (PMID 30943211, 2019).
infantile spasms syndrome (1 paper, 2025). "In conclusion, our findings confirmed that, with variable severity, both de novo heterozygous variants of CSNK1A1 underlay infantile spasms syndrome." (PMID 40156289, 2025).
lung diseases (1 paper, 2022). "For the majority of genes such as Elac2, Csnk1a1, Eif3a, Eif4g2, Tmed2 and Mpv17l, a role in the pathogenesis of lung diseases was indicated by previous studies, although their functions in the neonatal lung remain unexplored." (PMID 36271035, 2022).
macrocytic anemia (1 paper, 2024). Anemia that is characterized by increased red blood cell volume. "Typically, ribosomal protein S14 (RPS14) and casein kinase 1 alpha 1 (CSNK1A1) are associated with the dysplasia of erythrocytes, and RPS14 haploinsufficiency contributes to macrocytic anemia in mutant erythroblasts." (PMID 38616283, 2024).
prostate tumours (1 paper, 2024). "Additionally, the COSMIC database reports that 2.81% and 0.6% (498 samples) of prostate tumours have upregulated or down-regulation CSNK1A1 expression, respectively, in the TCGA dataset." (PMID 39001502, 2024).
refractory anemia (1 paper, 2023). "The CSNK1A1 gene encoding CK1α is located in the region deleted in myelodysplastic syndrome MDS 5q-, which is associated with refractory anemia." (PMID 36202990, 2023).
squamous cell lung carcinoma (1 paper, 2011). A carcinoma arising from squamous bronchial epithelial cells. "Casein kinase 1, alpha 1 (CSNK1A1) regulates protein turnover via initiation of translation via EIF2 and participates in wnt signalling; a homologue CSKNK2A1 has been previously identified as an independent predictor of survival in squamous cell lung cancer." (PMID 21297950, 2011).
Thrombocytopenia (1 paper, 2025). A reduction in the number of circulating thrombocytes. "CSNK1A1 haploinsufficiency in MDS-del(5q) leads to increased platelet counts, while recurrent somatic mutations of CSNK1A1 within the del(5q) CDR in MDS determine a homozygous CSNK1A1 defect with concurrent thrombocytopenia in the affected patients." (PMID 41440765, 2025).
cancer (63 papers, 2012 to 2025). A tumor composed of atypical neoplastic, often pleomorphic cells that invade other tissues. "Our signature genes, S100A10/p11, and CSNK1A1, are intricately linked to the development of various diseases and cancers." (PMID 39660117, 2024). "CK1α is a serine/threonine kinase encoded by CSNK1A1 on chromosome 5q32 with an oncogenic role in certain cancers." (PMID 38265263, 2024). "In such cancers, deletion of a region of chromosome 5q results in CK1α haploinsufficiency through loss of the CSNK1A1 gene, thereby sensitizing cells against further degradation of CK1α by lenalidomide." (PMID 33361334, 2021). "The active site mutation of CSNK1A1 defined here may similarly provide a mechanism for enhanced cancer cell proliferation and possible role for CSNK1A1 as a tumor suppressor." (PMID 27031502, 2016). "CSNK1A1 regulates various biological functions and conditions including development, cancer, circadian cycle, membrane transportation, immune response, neurodegeneration, autophagy, cell cycle, RNA processing, phagocytosis and cell death." (PMID 34615873, 2021). "In the last few years, CK1α, encoded by the CSNK1A1 gene, has been involved in cancer with a role that seems multifaceted." (PMID 28969692, 2017). "Csnk1a1 is known to regulate the Wnt signaling pathway, which is frequently disrupted in cancer and modulates cell growth, adhesion, and survival." (PMID 26829228, 2016). "All the down-regulated genes, in this Panel 3 showed their significant up-regulation in most of many types of cancers (TGM2, CSNK1A1, CTNNA1, NAMPT/Visfatin, TNFRSF1A, ETS1, SRC-1, FN1, APLP2, DMBT1/SAG, AIB1, AZIN1)." (PMID 23122428, 2012). "Therefore, we identify CSNK1A1 as a putative drug target in PDAC and reveal the potential of cancer-specific APA analyses to identify mechanisms of altered gene expression driving cancer pathogenesis." (PMID 32029502, 2020). "For example, several genes such as DKK1/2, CSNK1A1, INPP5D, and INPPL1 in the cases we discussed in detail are not present on the cancer panels we examined, yet their functional roles in respective signaling pathways are well-documented." (PMID 27245685, 2016).
tumor (60 papers, 2007 to 2026). "We describe the identification of a novel, tumor-specific missense mutation in the active site of casein kinase 1α (CSNK1A1) using activity-based proteomics." (PMID 27031502, 2016). "In this report, we describe the observation of a tumor-specific, mutated CSNK1A1 active-site peptide from close examination of LC-MS2 data and the subsequent verification that the CSNK1A1 gene was mutated." (PMID 27031502, 2016). "This suggests that elevated CSNK1A1 expression might be linked to a reduced presence of these immune effector cells in the tumor, potentially contributing to an immune-suppressive environment that could allow the tumor to evade immune surveillance." (PMID 40128844, 2025). "To distinguish whether the asparagine in the CSNK1A1 active site peptide was genetically encoded or the result of a post-translational event, we sequenced genomic DNA from the tumor sample presenting the apparent mutation." (PMID 27031502, 2016). "In this study, we evaluated the anti‐tumour effect of Csnk1a1 suppression in GBM cells in vitro and in vivo." (PMID 34216174, 2021). "To validate the dependency of tumor cells on CSNK1A1, KDM2A, and LTB4R2 in vitro, we generated the knockout (KO) of each gene by independently introducing two sgRNAs in two AD cell lines, NCI-H23 and A549." (PMID 34298691, 2021). "Csnk1a1, a negative regulator of the Wnt signalling pathway, functions as an important tumour suppressor." (PMID 34216174, 2021). "Several dozen clones were individually sequenced, resulting in the unambiguous identification of an AAC codon in CSNK1A1 in the 815zp tumor sample." (PMID 27031502, 2016). "The engineered enzyme also enabled an estimation of the ratio of mutant to wild type CSNK1A1 in the tumor sample." (PMID 27031502, 2016). "Across the complete data set, the average CSNK1A1 signal was four-fold higher in the tumor samples relative to control." (PMID 27031502, 2016). "An anomaly in the active-site peptide from CSNK1A1 was observed in a tumor sample that was consistent with an altered catalytic aspartic acid." (PMID 27031502, 2016). "This verified that, in the tumor sample, the catalytic amino acid for CSNK1A1 had been converted to an asparagine from an aspartic acid." (PMID 27031502, 2016). "Under our experimental conditions, the CSNK1A1 peptide elutes at 63.0 minutes, but signal apparently corresponding to CSNK1A1 was observed at both 59.8 minutes and 63.0 minutes in the tumor samples of this patient." (PMID 27031502, 2016). "The casein kinases CSNK1A1L and CSNK1E were down-regulated in neighbouring mucosa and up-regulated in tumour tissue, while CSNK1A1 was down-regulated in both tissue types." (PMID 27465361, 2016). "Conversely, CSNK1A1’s negative correlation with NK cells and its association with increased drug sensitivity to specific pathways emphasize its complex role in tumor immunity and therapy." (PMID 40128844, 2025). "Despite a low frequency of genetic aberrations and a small proportion of tumours showing transcriptional alterations, CSNK1A1 may still be an important driver of PCa for a subset of patients." (PMID 39001502, 2024). "Therefore, inhibiting Csnk1a1 activity is an effective method for suppressing the growth of tumour cells." (PMID 34216174, 2021).
tumor (continued). "Csnk1a1 may exert its anti‐tumour activity by inhibiting NF‐κB signalling pathway, which is the main signalling pathway of inflammation." (PMID 34216174, 2021). "Notably, the P value of overall survival calculated by Kaplan-Meier method that divided according to relative CSNK1A1 RNA expression in tumor tissue are both very close to 0.05." (PMID 29793495, 2018). "In a mouse model, ablation of Csnk1a1 caused the accumulation of β-catenin in the cytoplasm and nucleus activating many Wnt target genes although no tumor formation was observed." (PMID 23739040, 2013). "CSNK1A1 inhibits the canonical Wnt/β-catenin signaling pathway by promoting the degradation of CTNNB1, thereby promoting tumor cell growth." (PMID 32993576, 2020). "We confirmed some of these genes, including VRK1, CSNK1A1 and PIK3R4, were also essential in a range of other human CRC lines, suggesting that they may represent cell or tumor-type specific vulnerabilities." (PMID 31891587, 2019).
hematological disease (6 papers, 2017 to 2024). "Most of the research on CSNK1A1 focuses on hematological malignancies." (PMID 32993576, 2020). "The phylogenetically related Ser/Thr kinases CSNK1A1 (CK1α) and CSNK2 (CK2) have recently gained a growing importance in hematologic malignancies arising both from precursors and from mature blood cells." (PMID 28969692, 2017).
infection (5 papers, 2011 to 2022). The state of being infected such as from the introduction of a foreign agent such as serum, vaccine, antigenic substance or organism. "We next analyzed R. conorii spread in CSNK1A1-, CSNK2B-depleted cells and determined that the infection foci formed in the corresponding cells were indistinguishable from the ones observed in wild-type cells." (PMID 21853127, 2011).
adenocarcinoma (1 paper, 2019). A common cancer characterized by the presence of malignant glandular cells. "This would suggest a further single sporadic mutation, for example in Csnk1a1, could drive rapid progression to adenocarcinoma and metastasis in the KPN model, possibly by generating an inflammatory TME." (PMID 31526760, 2019).
CSNK1A1 also shares sentences with these, for which no sentence is quoted: multiple myeloma (11 papers); lymphoma (8); osteosarcoma (7); diffuse large B-cell lymphoma (6); liposarcoma (5); medulloblastoma (5); neurodegenerative disease (4); adenoma (3); invasive carcinoma (3); metastatic melanoma (3); ovarian carcinoma (3); Palmoplantar keratoderma (3); pancreatic cancer (3); prostate carcinoma (3); acute kidney injury (2); Alzheimer disease (2); Blood Cancer (2); Chronic Lymphocytic Leukemia (2); colorectal polyps (2); hematological cancers (2); lung adenocarcinoma (2); 5q deletion syndrome (1); acute leukemia (1); Arrhythmia (1); B cell lymphomas (1); clear cell renal cell carcinoma (1); colorectal (1); cyst (1); diabetes (1); Familial adenomatous polyposis (1).
A further 33 diseases each share a sentence with CSNK1A1 in 1 paper.